MIR518A1 (microRNA 518a-1)
Synonyms: hsa-mir-518a-1; MIRN518A-1; MIRN518A1; mir-518a-1
Gene: MicroRNA gene on chromosome 19 (53,731,006 to 53,731,090, forward strand). Ensembl gene ENSG00000207803.
Gene Ontology:
Biological process: miRNA-mediated post-transcriptional gene silencing